AQP1 (aquaporin 1 (Colton blood group))
Diseases named in the same sentence as AQP1 in open-access papers (continued):
Sharing a sentence is not in itself a finding about the gene and the disease.
prostate tumor (3 papers, 2010 to 2023). "Results revealed that AQP1 exhibited a positive correlation with the Gleason score; and with a progressive increase in the Gleason score AQP1 expression increases in prostate tumor." (PMID 36672280, 2023). "A large subgroup of primary prostate tumors has reduced levels of AQP3 and AQP1 as most of the lymph node metastasis samples." (PMID 20805891, 2010).
Renal cyst (3 papers, 2019 to 2021). A fluid filled sac in the kidney. "Some reports have revealed that AQP1 plays an important role in acute lung injury caused by endotoxic shock, delaying the occurrence of renal cyst, and acute lung and brain injury." (PMID 34814929, 2021). "It is reported that the overexpression of AQP1 inhibited renal cyst development by restraining Wnt/β-catenin signaling in an orthologous ADPKD mice model." (PMID 33796134, 2021). "AQP1 is expressed in the epithelia lining 71% renal cysts in human autosomal dominant polycystic kidney disease (ADPKD), 44% of which are derived from the proximal tubules." (PMID 33796134, 2021). "Our group has reported that AQP1 mediated the inhibition of renal cyst development by restraining Wnt/β-catenin signaling in an orthologous ADPKD mice model." (PMID 30654539, 2019). "AQP1 has great possibility to inhibit Wnt signaling and shows potential to retard the progression of renal cysts in clinic." (PMID 30654539, 2019).
schizophrenia (3 papers, 2015 to 2019). A major psychotic disorder characterized by abnormalities in the perception or expression of reality. "There are 4 genes, SOX9, HEPH, AQP1, and SDC3 as susceptible genes, and it was already reported that SDC3 has a weak association with schizophrenia in related GWAS." (PMID 27510319, 2016).
serous ovarian carcinoma (3 papers, 2018 to 2022). "A recent study, analysed the relationship between AQP1 expression and omental chemotherapy response in serous ovarian carcinoma." (PMID 35328186, 2022). "We evaluated the expression of β-catenin and AQP1 in the preoperative peritoneal biopsies of 32 patients with peritoneal carcinosis, in which a histological diagnosis of high grade serous ovarian carcinoma was made." (PMID 33807998, 2021). "Moreover, recent studies highlighted the potential role of β-catenin and Aquaporin-1 (AQP1) in serous ovarian carcinoma chemoresistance." (PMID 35328186, 2022).
sickle cell disease (3 papers, 2021 to 2024). Sickle cell anemias are chronic hemolytic diseases that may induce three types of acute accidents: severe anemia, severe bacterial infections, and ischemic vasoocclusive accidents (VOA) caused by sickle-shaped red blood cells obstructing small blood vessels and capillaries. "Single nucleotide polymorphisms in the priapism in patients with sickle cell disease are associated with TGFBR3, AQP1, and integrin-αv." (PMID 39335570, 2024). "Candidate drugs, perhaps similar to 5-PMFC with combined actions on both HbS stabilization and AQP1 ion channel inhibition, could be valuable starting points for generating affordable clinical options for treating sickle cell disease around the world." (PMID 35111062, 2021). "Novel therapeutic agents with combined actions on AQP1 ion channel inhibition and HbS stabilization could offer the desired slowing of dehydration and HbS polymerization, a goal of international interest for expanding the range of affordable clinical options for treating sickle cell disease." (PMID 35111062, 2021).
subarachnoid hemorrhage (3 papers, 2022 to 2025). A serious neurological disorder characterized by intracranial hemorrhage into the subarachnoid space. "AQP1 expression in the human brain was first observed under pathological conditions after subarachnoid hemorrhage, and in peritumoral tissue, with the protein being located mainly on the processes of reactive astrocytes." (PMID 36010640, 2022). "The level of AQP1 has been reported to be upregulated in subarachnoid hemorrhage, contusion, Creutzfeldt–Jakob disease, ischemia, multiple sclerosis, Alzheimer’s disease, epilepsy, and brain tumors." (PMID 36010640, 2022). "AQP1 expression was found to be elevated on astrocytic processes of reactive astrocytes in the brain after acute subarachnoid hemorrhage." (PMID 36010640, 2022).
Wilms tumor (3 papers, 2023 to 2024). An embryonal neoplasm characterized by the presence of epithelial, mesenchymal, and blastema components. "The exact role and underlying mechanisms of aquaporin-1 (AQP1) in the occurrence and development of nephroblastoma remain unclear." (PMID 38334883, 2024).
acute appendicitis (2 papers, 2017 to 2023). "We show here that in the progression of appendicitis there is an increase of AQP1 expression and, inevitably associated with this, an increase of water permeability of the entire enteric wall in the inflamed region." (PMID 28762291, 2017). "Severity of appendicitis can be correlated with water permeability measured by AQP1 protein expression and increase of ganglia count in a progressive manner." (PMID 28762291, 2017). "We show that AQP1 expression and water permeability in appendicitis correlate with the stage of inflammation and systemic infection parameters, leading eventually to perforation of the appendix." (PMID 28762291, 2017). "Severity of appendicitis and of systemic inflammation parameters can be positively correlated with water permeability, as measured by AQP1 protein expression in a progressive manner." (PMID 28762291, 2017). "In this study, we found a positive correlation of AQP1 expression in progressive appendicitis, and with this water permeability of the entire enteric wall, with the stage of inflammation." (PMID 28762291, 2017).
aneurysm (2 papers, 2022 to 2025). Bulging or ballooning in an area of an artery secondary to arterial wall weakening. "The proteins identified in the aneurysm wall include the structural fibulin-5 involved in elastin assembly, the anti-aggregatory and vasodilatory PGI2-producing enzyme prostacyclin synthase, and the water channel aquaporin-1 (AQP1)." (PMID 35203568, 2022).
autoimmune disease (2 papers, 2013 to 2019). A disorder resulting from loss of function or tissue destruction of an organ or multiple organs, arising from humoral or cellular immune responses of the individual to their own tissue constituents. "The list of over-represented diseases as well as list of mesh-diseases generated by Genomatix show that Aqp1 (along with other genes) participates in diseases such AKI, CNS disorder, inflammatory disorders and autoimmune diseases." (PMID 31417109, 2019).
autoimmune disorders (2 papers, 2023 to 2024). "We also discuss the presumed implication of AQP1-Abs in the development of autoimmune disorders, especially in the occurrence of CNS demyelination." (PMID 37629163, 2023). "Variable changes of AQP1 and AQP4 were found in biopsied CNS samples compared with normal controls reflecting the astrocytic reactions to stress within the context of GFAP autoimmunity." (PMID 38310187, 2024).
bacterial meningitis (2 papers, 2013 to 2022). Inflammation of the membranes surrounding the brain and spinal cord due to a bacterial infection. "Healthy CSF contains AQP1, whereas patients with neuro-inflammatory diseases such as bacterial meningitis have elevated AQP1 levels." (PMID 36204139, 2022). "A study detecting AQP1 and AQP4 in CSF determined that the mean concentration of AQP1 in CSF was significantly higher in patients with bacterial meningitis (BM), AQP4 was also greater but not significantly so." (PMID 23659378, 2013).
cancers of the stomach (2 papers, 2018 to 2019). "However, AQP1 and AQP8 showed a trend toward decreased expression in normal gastric tissues, whereas its high and medium expression was documented respectively in cytoplasmic and membranous region of gastric tumor tissues." (PMID 29678898, 2018).
choroid plexus carcinoma (2 papers, 2014 to 2022). A malignant neoplasm arising from the choroid plexus. "And in low-grade choroid plexus papillomas, AQP1 expression had no significant polarity, no clear expression pattern, and each patient had a significant difference, and AQP1 expression on the normal choroid plexus had a significant polarity completely opposite, but this study was unattended." (PMID 36340696, 2022). "Studies have shown that AQP1 expression is strong and diffuse in low-grade choroid plexus papillomas, but not in high-grade choroid plexus papillomas, which may be associated with the disappearance of papillary structures in high-grade tumors." (PMID 36340696, 2022).
choroid plexus tumors (2 papers, 2014 to 2025). "High expression of AQP1 has been observed in choroid plexus tumors." (PMID 41270129, 2025).
chronic pancreatitis (2 papers, 2018). A chronic inflammatory process causing damage and fibrosis of the pancreatic parenchyma. "Bile acid treatment dose- and time-dependently decreased mRNA and protein expression of AQP1 and reduced expression of this channel was also demonstrated in patients suffering from acute and chronic pancreatitis." (PMID 30050452, 2018). "AQP1 is overexpressed in the pancreatic ducts of patients with autoimmune pancreatitis, which showed chronic pancreatitis characterized by a severely impaired secretion of digestive enzymes from acinar cells as well as pancreatic fluid and HCO3- secretion from ducts." (PMID 29675407, 2018). "Changes in both AQP1 and AQP12 have been observed during the onset of acute and chronic pancreatitis, reflecting their potential as markers of pancreatic damage." (PMID 29675407, 2018).
chronic superficial gastritis (2 papers, 2016 to 2023). "Collectively, these results indicate that the expression of several subtypes of AQPs (AQP1, AQP3, AQP4, AQP5, AQP7 and AQP11) is upregulated by gastritis, and more studies are essential to investigate their potentials as diagnostic biomarkers and drug targets for gastritis therapy." (PMID 27589719, 2016).
cognitive deficits (2 papers, 2022 to 2026). "At the molecular level, MASLD altered the expression of key hippocampal genes-including TCF7L2, LCN2, and AQP1-impacting immune response, lipid metabolism, and apoptotic pathways, which collectively contributed to cognitive deficits." (PMID 41674921, 2026).
colitis (2 papers, 2013 to 2016). Inflammation of the colon. "At the same time, pharmacological treatment with sodium butyrate, a short-term fatty acid (SCFA) that is considered a fuel for intestinal epithelial cells, reverted the pathologic conditions, reducing the effect of colitis by normalizing AQP1 expression." (PMID 27472320, 2016). "Our unpublished data obtained on DSS-induced colitis in mice show a slight but significant reduction of AQP1 expression in cecum tracts (data not shown), determined using an antibody that recognized a specific band at 28 kDa and two other bands at 55 and 65 kDa, respectively." (PMID 27472320, 2016).
coronary artery disease (2 papers, 2018 to 2024). "Our findings suggest AQP1 blockade or Aqp1 deletion as effective senotherapeutic strategy with potential of pro-angiogenic efficiency for recovery of ischemic vascular diseases such as coronary artery disease and peripheral arterial disease in older adults." (PMID 39180980, 2024). "Work in this area in ongoing; thus, once identified, clinically safe and effective AQP1 inhibitors may represent a novel class of antiplatelet drugs for the management of acute coronary syndrome, coronary artery disease, and stroke." (PMID 29769447, 2018).
Creutzfeldt-Jakob disease (2 papers, 2013 to 2020). "Generally, Aqp1 and/or Aqp9 are elevated in hypertrophied, GFAP overexpressing astrocytes in a number of pathological states, such as ischemic or traumatic brain injury, Alzheimer’s or Creutzfeldt-Jakob diseases." (PMID 23940528, 2013).
dialysis (2 papers, 2019 to 2025). "This suggests that common AQP1 promoter variants may influence water channel expression in the peritoneum, affecting water transport, ultrafiltration, and prognosis in PD-treated kidney failure patients." (PMID 39724420, 2025). "Another recent study on a large cohort of PD patients with kidney failure further substantiated the impact of AQP1 genotype variation on water channel expression in the peritoneal membrane, influencing water transport, ultrafiltration, and patient prognosis." (PMID 39724420, 2025). "The water channel Aquaporin 1 (AQP1) plays a fundamental role in water ultrafiltration during peritoneal dialysis (PD) and its reduced expression or function may be responsible for ultrafiltration failure (UFF)." (PMID 30970608, 2019).
endometrial adenocarcinoma (2 papers, 2022 to 2025). "A possible interaction between AQP1 and the vascular endothelial growth factor (VEGF) signaling pathway was reported, implicating AQP1 in tumor angiogenesis and endometrial adenocarcinoma progression." (PMID 39941100, 2025).
endometrioid adenocarcinoma (2 papers, 2021 to 2022). An adenocarcinoma characterized by the presence of malignant glandular epithelial cells resembling endometrial cells. "Moreover, high AQP1 expression is associated with poorer prognosis in mucinous and endometrioid carcinomas." (PMID 33807998, 2021). "The AQP1/IMD ratio was significantly higher in endometrioid adenocarcinoma and positively correlated with the histologic grade, invasion, and metastasis." (PMID 36230654, 2022).
endotoxemia (2 papers, 2019). "After endotoxemia, water intake and urinary output in AQP1-KO mice were significantly increased, and urinary osmolality was significantly decreased compared with WT mice." (PMID 31023968, 2019). "Urinary sodium excretion and fractional sodium excretion were higher in AQP1-KO mice compared with WT mice in endotoxemia, which were accompanied by more severe tubular injury." (PMID 31023968, 2019). "A study reported that endotoxemia-induced AKI is more severe in AQP1 knockout mice, implying the importance of AQP1 channel." (PMID 30654539, 2019). "The higher serum osmolality in AQP1-KO mice during endotoxemia in the absence of water repletion was associated with higher AQP2, AQP3, and Na+-K+-2Cl− cotransporter type 2 expression and a lower Na+/H+ exchanger type 3 protein expression than that in WT mice during endotoxemia." (PMID 31023968, 2019).
gastric adenocarcinoma (2 papers, 2018 to 2019). "An increase in AQP1 expression of resected gastric adenocarcinoma correlated with an increase in apoptosis." (PMID 31013775, 2019).
head and neck cancer (2 papers, 2017 to 2022). A primary or metastatic malignant neoplasm affecting the head and neck. "Reactivation of endogenous AQP1 has been investigated as a strong target to establish gland regeneration in injured glands by collateral irradiation of head and neck cancer patients." (PMID 28766180, 2017).
hemangioendothelioma (2 papers, 2011 to 2017). A vascular proliferation characterized by the presence of prominent endothelial cells and the formation of vascular channels. "Functional response of the Aqp1 promoter was assessed in terms of the luciferase activity observed upon transfection in a murine hemangioendothelioma cell line (EOMA)." (PMID 22174795, 2011).
Hepatic cancer (2 papers, 2015 to 2020). "AQP1 is thus suggested as the potential diagnostic factor to differentiate diagnosis in liver cancer pathologies." (PMID 25886458, 2015).
hepatopulmonary syndrome (2 papers, 2019 to 2024). Hepatopulmonary syndrome (HPS) is a lung disease characterized by widening of arteries and veins (dilatation) in the lungs in people who have chronic liver disease. "A caspase-3 inhibitor prevented pulmonary injury induced by common bile duct ligation, an experimental model of hepatopulmonary syndrome, and decreased apoptosis and endothelial AQP1 levels." (PMID 39335570, 2024). "In rats with hepatopulmonary syndrome, AQP1 enhanced pulmonary arterial smooth muscle cell (PASMC) migration via the p38 MAPK pathway, which may represent a potential therapeutic strategy for the regulation of pulmonary vascular remodelling." (PMID 31529146, 2019).
hydrarthrosis (2 papers, 2015 to 2019). Accumulation of watery fluid in the cavity of a joint. "Up-regulated AQP1 found in the inflamed synovial tissues of RA patients might play a potential pathological role in hydrarthrosis and joint swelling." (PMID 31480869, 2019).
hydrocele (2 papers, 2014 to 2023). "Western blotting: AQP1 protein expression in the tunica vaginalis was significantly higher in patients with adult-onset hydrocele testis (n = 7) than in the controls (n = 5)." (PMID 24817884, 2014). "AQP1 protein expression in the tunica vaginalis was significantly higher in patients with adult-onset hydrocele testis than in the controls." (PMID 24817884, 2014). "The densities of AQP1-expressing capillaries and lymphatic vessels were similar between the tunica vaginalis of the controls and those of hydrocele patients." (PMID 24817884, 2014). "As shown in a scatter diagram, the expression of AQP1/GAPDH was similar between the two cases with hydrocele fluid of less than 10 mL and other cases with more than 100 mL." (PMID 24817884, 2014). "There was a significant decrease in the methylation rate at one of the CpG sites in the CpG island associated with the AQP1 gene in the tunica vaginalis of patients with non-communicating hydrocele testis." (PMID 38021552, 2023). "We performed genetic and epigenetic analyses of the AQP1 gene in the tunica vaginalis of patients with adult-onset non-communicating hydrocele testis to elucidate the cause of enhanced AQP1 protein expression." (PMID 38021552, 2023). "This may increase AQP1 protein expression and contribute to the formation of hydrocele testis." (PMID 38021552, 2023). "Thus, we performed genetic and epigenetic analyses of the AQP1 gene in the tunica vaginalis of patients with adult-onset non-communicating hydrocele testis to elucidate the cause of enhanced AQP1 protein expression." (PMID 38021552, 2023). "In the present study, the relationship between genetic and epigenetic changes in the AQP1 gene and AQP1 protein production was not directly examined, but hydrocele testis was analyzed as a target factor." (PMID 38021552, 2023). "Frozen tunica vaginalis specimens from patients with adult-onset primary hydrocele testis and control male nonhydrocele patients were subjected to Western blot analysis for the detection of AQP1 and AQP3 proteins." (PMID 24817884, 2014). "However, the reason why AQP1 protein expression in the tunica vaginalis is enhanced in patients with non-communicating hydrocele testis has remained unclear." (PMID 38021552, 2023). "Water channel aquaporin 1 (AQP1) protein expression is enhanced in the tunica vaginalis of patients with adult-onset non-communicating hydrocele testis and may contribute to the development of non-communicating hydrocele testis." (PMID 38021552, 2023). "We previously reported that AQP1 protein expression is enhanced in the tunica vaginalis of patients with adult-onset non-communicating hydrocele testis compared with controls and may contribute to the development of non-communicating hydrocele testis." (PMID 38021552, 2023).